LEP (leptin)
Diseases named in the same sentence as LEP in open-access papers (continued):
Sharing a sentence is not in itself a finding about the gene and the disease.
Insulin resistance (continued). "Taken all together, it could be speculated that the lower expression of Sam68 in PCOS may, in part, be responsible for insulin resistance, and as a consequence, the resistance to leptin action on aromatase expression in GCs from PCOS women." (PMID 36139396, 2022). "Congenital and acquired lipodystrophy share a common pathophysiology: adipose tissue dysfunction, an alteration that results in most cases in hypertriglyceridemia, ectopic fat accumulation, insulin resistance, chronic inflammation and low levels of leptin and adiponectin." (PMID 36432429, 2022). "In rats fed high fat diets, M. charantia freeze-dried unripe fruit juice (0.75%) could improve insulin resistance, as well as lower serum insulin and leptin." (PMID 35408574, 2022). "Treatment of ob/ob mice with physiological doses of leptin (to match WT serum levels) reverses insulin resistance, as it does in lipodystrophic mice and humans, suggesting this could be the mechanism of action of muscle mass accretion with leptin treatment." (PMID 35844058, 2022). "In fact, studies based on dietary surveys have associated a low intake of exogenous AGEs with lower insulin resistance, TNF alpha levels, peripheral cell mononuclear cells and leptin concentration, as well as higher adiponectin, which ultimately means less proinflammatory activity." (PMID 36615860, 2022). "In fact, a recent review described that hypothyroid disease may cause insulin resistance possibly through an alteration of GLUT4 translocation and the effects of leptin, and an elevation of free fatty acids." (PMID 35137143, 2022). "However, this study did not incorporate dietary intake analysis and measurement of biological metabolic markers, such as insulin resistance index, leptin, and adiponectin." (PMID 36014832, 2022). "The lack of a role for leptin deficiency or insulin resistance in affecting urine oxalate excretion in ob/ob mice is important for several reasons." (PMID 35851836, 2022). "Leptin and adiponectin have opposite effects on subclinical inflammation and insulin resistance." (PMID 36014832, 2022). "The mechanism is unclear but, in both prostate and renal cancers and insulin resistance, is associated with high circulating levels of insulin-like growth factors (ILGF) and high levels of the hormone leptin - which activates several carcinogenic cellular pathways." (PMID 35547428, 2022). "Hypothalamic inflammation contributes to leptin and insulin resistance." (PMID 35911732, 2022). "Indeed, in patients with congenital generalised lipodystrophy, leptin treatment, which is known to improve metabolic complications including insulin resistance, has been recently shown to attenuate cardiac hypertrophy and increase contractile function." (PMID 35384404, 2022). "Antipsychotic-induced leptin and insulin resistance may be related to elevated hypothalamic ER stress." (PMID 36188456, 2022). "Adipocyte-specific Nfe2l2-KO mice with a leptin-deficient ob/ob background (a model with an extremely positive energy balance) led to reduced WAT mass but with severe metabolic syndrome and serious insulin resistance, hyperglycemia, and hypertriglyceridemia." (PMID 35204118, 2022). "Leptin and adiponectin have opposite impacts on insulin resistance and inflammation." (PMID 36289903, 2022). "Elevated concentrations of TNF-α, IL-1b, IL-6 and leptin may also worsen insulin resistance and increase fetal overgrowth." (PMID 35957820, 2022). "Moreover, the biological function of Fetuin B in promoting insulin resistance and glucose intolerance was consistent with the detrimental effects of leptin in the liver, as defined in aged or obese models." (PMID 35896788, 2022). "There is evidence that excessive visceral fat accumulation, manifested as central obesity, can impair insulin sensitivity and even result in insulin resistance, and reduced insulin sensitivity interferes with leptin signaling, which plays in important role in puberty initiation." (PMID 35846287, 2022).
Insulin resistance (continued). "Furthermore, adiponectin in combination with leptin has been shown to completely reverse insulin resistance in mice." (PMID 35889872, 2022). "Moreover, leptin impacts on pancreatic beta cells, immune cells and muscle cells and modulate glucose metabolism, inflammatory processes and insulin resistance." (PMID 36482911, 2022). "The ratio of adiponectin to leptin is a reliable biomarker for insulin resistance and diabetes." (PMID 35928844, 2022). "Third, we used this LC–MS assay to determine that leptin deficiency and insulin resistance do not contribute to hyperoxaluria in ob/ob mice because leptin replacement or pioglitazone treatment did not affect urine oxalate excretion." (PMID 35851836, 2022). "The mechanism of leptin contribution to the development of insulin resistance may lie in its capacity to phosphorylate insulin receptor 1 substrate (IRS1) serine residues, which downregulates insulin signaling." (PMID 35682958, 2022). "In addition, for AGPAT2 and BSCL2 KO mice, leptin replacement or AT surgical implantation strongly improved the metabolic phenotype including insulin resistance, liver steatosis and renal injuries." (PMID 35250856, 2022). "K-means clustering identified two clusters of increasing metabolic deviance evidenced by cluster differences in the plasma levels of leptin (40.36 (29.97) vs. 27.59 (25.58) μg/L) and the degree of insulin resistance (SSPG concentration: 161.63 (65.27) vs. 125.72 (66.81) mg/dL)." (PMID 35492025, 2022). "However, insulin resistance, inflammation, visceral adiposity, autonomic dysfunction, and leptin resistance deserve to be commented on." (PMID 35268504, 2022). "The administration of hydroalcoholic extract of Urtica dioica at doses of 50, 100, and 200 mg/kg/day for 2 weeks to fructose-induced insulin resistance Wistar rats showed a dose-dependent decrease in serum glucose, low density lipoprotein, leptin, and fasting insulin resistance index." (PMID 36014458, 2022). "By isomerizing linoleic acid to conjugated linoleic acid, Butyrivibrio could inhibit leptin and adiponectin secretion and glucose absorption, and increase anaerobic respiration of glucose, subsequently inducing insulin resistance." (PMID 36140683, 2022). "The markedly decreased circulating leptin levels observed in this study may not only contribute to improved insulin resistance, but may also alleviate inflammation and cardiovascular damage." (PMID 36140169, 2022). "Increasing insulin resistance seen throughout gestation is primarily the result of placental secretion of tumor necrosis factor alpha (TNFa) and small contributions from maternal plasma cortisol and leptin." (PMID 36584051, 2022). "Furthermore, activation of IKKβ-NF-κB signaling through ER stress in the hypothalamus is associated with dysfunction of SOCS3 signaling, which means central leptin and insulin resistance." (PMID 36188456, 2022). "The possible mechanism of the relationship between VAI and insulin resistance is as follows:Visceral adipocytes secrete adipose-specific cytokines, such as leptin and adiponectin, as well as inflammatory cytokines (tumor necrosis factor-α and interleukin 6), which increase IR." (PMID 35937809, 2022). "Considering adipose tissue is a hormonally active tissue, some adipokines may be associated with the metabolic state of the child – as such, the leptin/adiponectin ratio may be a useful indicator of insulin resistance." (PMID 36387906, 2022). "Hence, we aimed to investigate the relationship between leptin levels and insulin resistance in the population aged between 50 and 85 years in Taiwan." (PMID 36143007, 2022). "As follow-up analysis, hierarchical multiple regression was used to assess the interaction effect of continuous insulin resistance with serum Mg2+ and analyzed by multivariable linear regression on the association of outcome variables: HbA1c, BMI, Log10 hs-CRP and Log10 Leptin." (PMID 35440685, 2022).
Insulin resistance (continued). "In addition, insulin resistance, increased and decreased leptin and adiponectin levels, as well as recruitment of macrophages, T lymphocytes, and production of IL-1β, IL-4, IL-6, IL-17, and TNF-α, lead to local and systemic chronic low-grade inflammation." (PMID 35379852, 2022). "Indeed, P. gingivalis LPS exposure leads to increased secretion of resistin and leptin involved in insulin resistance and decreased secretion of adiponectin recognized as an insulin-sensitizing molecule." (PMID 35327570, 2022). "In one study, a significant alteration in metabolic status was reported after 10 days, including systolic blood pressure, glucose, high density lipoprotein cholesterol, leptin, insulin and insulin resistance, however, changes in FMD were only seen after 6 months." (PMID 35887817, 2022). "In addition, it is associated with metabolic factors such as excess body weight, insulin resistance, higher levels of circulating leptin, and markers of inflammation." (PMID 35999624, 2022). "Two ceramides, Cer/AP(t15:2/16:2) and Cer/AS(d15:2/16:2), were increased in the M group while RPE decreased these levels, indicating that the RPE might improve the sensitivity of leptin and insulin resistance in diabetes." (PMID 35741945, 2022). "In humans, insulin resistance is associated with elevated serum leptin levels, independent of body mass." (PMID 35386146, 2022). "Moreover, animal and human studies show that leptin and insulin resistance act on hypothalamic receptors and appetite circuits, leading to postnatal hyperphagia, decreased satiety, and subsequent development of metabolic syndrome." (PMID 35706903, 2022). "The authors proposed that the reduction in height velocity under leptin treatment may be due to the drop in insulin levels that follows the improvement in insulin resistance." (PMID 34002033, 2021). "The finding of the high levels of triacylglycerides (TGs) after HZE exposure which rapidly cross the blood brain barrier and bind to leptin and insulin receptors may play a role in insulin resistance." (PMID 34290258, 2021). "In addition, it increases the secretion of leptin, resistin, and inhibitor-1 of plasminogen activation, which promotes insulin resistance." (PMID 34568974, 2021). "LMF-HSFx may modulate leptin-adiponectin axis in adipocytes and hepatocytes, then regulate lipid and glycogen metabolism, decrease insulin resistance and is against NAFLD." (PMID 33809062, 2021). "Impaired activation of GIPR and GLP-1R contributes to a decrease in the secretion of insulin and ghrelin and, on the contrary, to an increase in leptin and glucagon in the circulation, which contributes to the formation of insulin resistance in obese patients with T2DM." (PMID 33959145, 2021). "Negative genetic correlations were documented between anorexic patients and metabolic traits such as type 2 diabetes, insulin resistance, blood plasma insulin, leptin, and a significant positive genetic correlation was found with high-density lipoprotein (HDL) cholesterol." (PMID 33953692, 2021). "Accordingly, ghrelin was found to negatively correlate with leptin and insulin resistance." (PMID 34374968, 2021). "Likewise, there was a shift in the insulin secretory pattern, improvement in insulin resistance, and a profound lowering of leptin levels." (PMID 34950778, 2021). "Leptin also has important pro-inflammatory effects, which may play a role in insulin resistance and hypertension." (PMID 34966295, 2021). "A relationship has been observed between increased concentration of leptin and the symptoms of the metabolic syndrome, including atherosclerosis, insulin resistance, and high blood pressure, which may result in cardiovascular disease." (PMID 34371845, 2021). "the metabolic risk markers and insulin resistance indicators of BC survivors were significantly improved, while the reduction in leptin was not significant while adiponectin was significantly reduced." (PMID 34350120, 2021).
Insulin resistance (continued). "These negative genetic correlations corroborate the epidemiological associations, previous research findings and clinical observations of CRF and PA and body composition, lipid profile, adipocytokines, fasting insulin and insulin resistance and leptin, T2D and CAD." (PMID 34753499, 2021). "Additionally, knocking down the ALPL gene decreased the expression of leptin, which plays a key role in adipocyte systemic signaling and insulin resistance." (PMID 34198561, 2021). "Additionally, Riceberry flour does not contain gluten and some studies have reported that gluten-free diets can help to prevent diabetes by reducing leptin and insulin resistance and increasing beta cell volume." (PMID 34945488, 2021). "Leptin, adiponectin, and the leptin/adiponectin ratio are correlated with insulin resistance." (PMID 35185786, 2021). "Briefly, in vivo, LMF-HSFx may enhance the leptin and adiponectin expression in adipocytes and decreases insulin resistance." (PMID 33809062, 2021). "In addition, leptin plays a major role in liver lipid handling, as recombinant leptin reverses insulin resistance and hepatic steatosis in lipodystrophic patients." (PMID 33799409, 2021). "The majority of the available research demonstrates that intermittent fasting is effective at reducing body weight, decreasing fasting glucose, decreasing fasting insulin, reducing insulin resistance, decreasing levels of leptin, and increasing levels of adiponectin." (PMID 33531076, 2021). "High levels of leptin and resistin occurring in obese individuals, lead to the emergence of insulin resistance, whereas adiponectin may prevent it." (PMID 34684622, 2021). "Insulin resistance is associated with an increase of TNF-α, IL-1α, IL-1β, IL-6, and leptin." (PMID 34970568, 2021). "Reduction of insulin resistance through PAR-γ/GLUT4-leptin/TNF-α signaling pathway." (PMID 34299610, 2021). "Leptin-deficient mice have growth problems and severe insulin resistance, while humans with leptin deficiency do not have growth restriction and moderate insulin resistance." (PMID 34504472, 2021). "Moreover, insulin resistance and leptin can lead to CVD events, but further research needs to be conducted." (PMID 33946540, 2021). "In addition, TNF-α increases circulating levels of leptin and resistin when interacting synergistically with IL-6, favoring increased peripheral insulin resistance and greater chances of developing T2DM." (PMID 33520042, 2021). "A randomized cross-over clinical trial based on 61 obese children with NAFLD proved that daily consumption of 100 mL of tomato juice for 60 days could improve hepatic steatosis, insulin resistance, levels of leptin, and lipid profiles." (PMID 33728021, 2021). "The previous report indicated that leptin administration may alleviate insulin resistance in patients with lipodystrophy." (PMID 34441028, 2021). "Leptin accumulation can promote leptin and insulin resistance, leading to hyperglycemia, and SARS-CoV-2 may further contribute to hyperglycemia, though this mechanism is less clear and needs further exploration." (PMID 34698139, 2021). "On the contrary, increased visceral fat results in accumulation of proinflammatory cytokines and free fatty acids that aggravate insulin resistance and dysregulated leptin signaling could inhibit hypothalamic–pituitary–gonadal (HPG) axis function." (PMID 34135863, 2021). "Although we neither observed WAT fibrosis, nor local or systemic inflammation, HFD‐induced glucose intolerance, insulin resistance, and leptin production consistent with increased fat mass and adipocyte hypertrophy together with organization of immune cells in crown‐like structures." (PMID 34278707, 2021). "Interestingly, the high leptin and low adiponectin levels together with the increased plasma lactate are early important markers that differentiate obese subjects with insulin resistance from their metabolic healthy counterpart." (PMID 34457110, 2021).
Insulin resistance (continued). "Moreover, delayed intervention with ASEC, PRO, or ASEC + PRO reversed HFD-induced impaired glucose tolerance, insulin resistance, and elevated serum leptin and resistin levels." (PMID 34579036, 2021). "In addition, overexpression of leptin was shown to rescue insulin resistance in diabetic mouse models." (PMID 33755309, 2021). "Furthermore, overweight is associated with earlier pubertal timing due to accelerated gonadal function stemming from increased insulin resistance, androgens, and leptin levels." (PMID 34992577, 2021). "MetS may favor cancer occurrence in three ways-insulin resistance, deregulation of leptin and activation of proinflammatory factor system." (PMID 33468224, 2021). "Thus, extreme leptin resistance in db/db mice leads to bulimia and consequent morbid obesity, as well as reproductive dysfunction and severe insulin resistance." (PMID 34836432, 2021). "Spearman's correlation analysis showed that these amino acid levels were positively correlated with metabolic characterization, including food intake, FBG, glucose tolerance, insulin resistance, and serum leptin and insulin levels, among which glycine had the strongest correlation." (PMID 33637880, 2021). "In mice models with systemic inflammation and insulin resistance, there is accumulation of IL-6/IL-17 co-expressing T cells in the adipose tissue; these cells enhance leptin production, which eventually acts in synergy with IL-6 and IL-17 to promote Th17 differentiation." (PMID 34631754, 2021). "In addition, the prebiotic groups displayed lower leptin levels, fasting glucose, fasting insulin and insulin resistance compared to the ABT group." (PMID 33445530, 2021). "hydroalcoholic extract decreased blood glucose, insulin resistance, leptin and IL-6 levels, lipid profile, and vascular dysfunction, while increasing the expression of insulin signaling proteins in skeletal muscle, adipose tissue and plasma glucagon like peptide-1 (GLP-1) levels." (PMID 33435282, 2021). "Elevated levels of BCAAs, observed here after caloric restriction but not leptin administration in congenital leptin deficiency, have been repeatedly associated with insulin resistance, diabetes, and cardiovascular disease in multiple cohorts." (PMID 32392278, 2020). "Similarly, positive associations were observed for markers of insulin resistance (HOMA-IR, fasting insulin, reduced insulin sensitivity, increased leptin and reduced adiponectin) and systemic inflammation (c-reactive protein)." (PMID 32958048, 2020). "In addition, the results demonstrate that a 1 point BMI increment raises leptin levels by 1.431 ng/mL and increases insulin resistance about 0.1 units." (PMID 33680012, 2020). "In contrast there was a trend for lower plasma adiponectin concentrations pre-necropsy in growth-restricted versus normal birthweight males (P = 0.053) and the plasma adiponectin: leptin ratio, a putative marker of insulin resistance, was reduced (P = 0.04) in the former group." (PMID 32059008, 2020). "However, the evidence in human studies suggesting leptin’s role is independent from its actions on body weight was observed in lipodystrophic individuals where leptin replacement therapy reversed insulin resistance." (PMID 32131811, 2020). "It is, therefore, speculated that low leptin levels due to reduced adiposity may give rise to insulin resistance in lipodystrophies." (PMID 32491965, 2020). "The corresponding changes of adiponectin and leptin levels could be coupled with a decrease in insulin resistance." (PMID 31859911, 2020). "The association between leptin and type 2 diabetes is not only mediated through insulin resistance, but it is present exclusively among those without abdominal obesity." (PMID 32131811, 2020). "Furthermore, the alb-SREBP-1c mice displayed hepatic insulin resistance and had higher levels of plasma insulin, leptin, triglycerides, and free fatty acids versus C57Bl6 mice." (PMID 32532003, 2020).